PYY (peptide YY)
Diseases named in the same sentence as PYY in open-access papers (continued):
Sharing a sentence is not in itself a finding about the gene and the disease.
diseases of the pancreas (1 paper, 2019). "PYY and PP are mainly contained in the pancreas and gastrointestinal mucosa and, in particular, the pancreatic polypeptide is related to diseases of the pancreas, such as pancreatitis." (PMID 30935107, 2019).
dyslipidaemia (1 paper, 2021). "Thus, we observed that the risk of developing dyslipidaemia was more associated to lunch and dinner instead of breakfast because at these times of the days (lunch and dinner) it is expected that GLP-1 and PYY would be at lower levels than in the morning due to their circadian rhythm." (PMID 34952593, 2021).
gastric tumor (1 paper, 2023). "PYY blocked the growth of breast tumor cells (e.g., MCF-7, ZR-75), and the same effect was observed in gastric tumor cell lines." (PMID 37373115, 2023).
gastroparesis (1 paper, 2024). Paralysis of the muscles of the stomach wall resulting in delayed emptying of the gastric contents into the small intestine. "The probable reason why group T1 (< 6 months) presents more intense nausea than group T2 (≥ 6 to 12 months) is due to the important stimulus of incretins (GLP-1, PYY, etc.), initial gastroparesis that regresses over time." (PMID 37946012, 2024).
glioblastoma (1 paper, 2025). The most malignant astrocytic tumor (WHO grade IV). "The neuropeptide-related genes, including PPY and members of the NPY family (e.g., NPY, NPY1R, NPY2R, NPY4R, NPY5R, PYY), form a distinct cluster characterized by strong co-expression and shared pathway interactions, indicating a potential role in neuroendocrine signaling relevant to glioblastoma." (PMID 40725410, 2025).
hepatic carcinoma (1 paper, 2023). "PYY blocked human HepG2 hepatic carcinoma cell growth in an experimental animal model; PYY decreased tumor volume/weight and cAMP level." (PMID 37373115, 2023).
Hirsutism (1 paper, 2017). Abnormally increased hair growth referring to a male pattern of body hair (androgenic hair). "Plasma PYY level was significantly negatively correlated with waist circumference, WHR, hirsutism score, testosterone, PPG, ALT and AST, whereas, significantly positively correlated with neutrocyte count and HOMA-beta." (PMID 28293234, 2017).
Hypoglycemia (1 paper, 2018). A decreased concentration of glucose in the blood. "Using standard and high-specificity immunoassays and mass spectrometry, we observed elevated GLP-1, peptide YY (PYY), and insulin levels after glucose ingestion in PTG patients, with consequent hypoglycemia in several participants." (PMID 29548882, 2018).
intestinal motility disorders (1 paper, 2024). "Clinical studies have demonstrated a significant reduction in the concentration of PYY and the number of PYY cells in the colons of patients with IBS, potentially contributing to intestinal motility disorders and visceral hypersensitivity in these individuals." (PMID 39766350, 2024).
ischaemia (1 paper, 2006). "Further studies are required to assess these associations, in particular whether the heightened PYY response to nutrients predisposes patients to intestinal ischaemia." (PMID 17173662, 2006).
manic episodes (1 paper, 2025). "ROC analysis was conducted to elucidate the relationship between asprosin and PYY concerning both the disease manifestation and manic episodes in individuals diagnosed with the condition." (PMID 39941681, 2025). "Furthermore, the analysis results substantiated that asprosin (AUC ± SE; 95% CI; 0.775 ± 0.048; 0.682–0.869) and PYY (AUC ± SE; 95% CI; 0.760 ± 0.050; 0.662–0.865) were significantly correlated with manic episodes in BD-I." (PMID 39941681, 2025). "Furthermore, we observed that diminished PYY levels exhibited a stronger correlation with BD-I and manic episodes." (PMID 39941681, 2025). "Moreover, PYY may serve as a state marker for manic episodes." (PMID 39941681, 2025).
mental disorder (1 paper, 2024). A disease that has its basis in the disruption of mental process. "For example, full-length PYY binds with similar affinity to all Y receptors, but the predominant circulating form of PYY-immunoreactivity, truncated PYY3–36, preferentially binds to the Y2 receptor, a G protein-coupled receptor implicated in appetite and feeding control, mood, and mental disorders." (PMID 38961511, 2024).
migraine (1 paper, 2022). "Other receptors with possible indirect effects on migraine are parathyroid hormone 1 receptor (PTH1R) and PTH2R, which mediates calcium and phosphate homeostasis, and NPY5R that acts as receptor for neuropeptide Y (NPY), PYY, and PYY, and influences eating." (PMID 35453627, 2022).
mood disorder (1 paper, 2012). A cognitive disorder a disturbance in which the person's mood is hypothesized to be the main underlying feature. "The results of experimental studies have also suggested that gastrointestinal tract hormones, such as ghrelin and peptide YY (PYY), participate in mood disorders development." (PMID 22844280, 2012).
morbid obesity (1 paper, 2017). An excess of body weight, normally defined as an individual with a body mass index greater than 35 or a body weight greater than one hundred percent of ideal body weight. "However, at the beginning of the hedonic session of eating and after the exposure to the palatable food, such blunted PYY secretion seems to be a distinctive ‘paradoxical’ response in PWS, which is not present in lean subjects and patients with essential morbid obesity)." (PMID 28659728, 2017).
neural tube defect (1 paper, 2021). A congenital defect characterized by failure of the neural tube to close completely; this results in the presence of openings in the brain or spinal cord. "However, it is important to note that PYY is involved in other aspects of development; and therefore, its increased expression because of PFOS exposure may be a result of and/or lead to other developmental problems like neural tube defect." (PMID 33044770, 2021).
Osteopenia (1 paper, 2021). Osteopenia is a term to define bone density that is not normal but also not as low as osteoporosis. "PYY-deficient mice (Pyy(−/−)) have osteopenia with a reduction in trabecular bone mass and a deficit in bone strength." (PMID 34948466, 2021).
postmenopausal osteoporosis (1 paper, 2020). Metabolic disorder associated with fractures of the femoral neck, vertebrae, and distal forearm. "This study aims to review further the effect of Zhuang-Gu-Fang on the ultrastructure of osteoblasts, bone metabolism balance, and serum Leptin, Ghrelin, and PYY concentration in ovariectomized rats and explore the treatment of postmenopausal osteoporosis with Zhuang-Gu-Fang-related mechanisms." (PMID 33281915, 2020). "Conclusively, the study proved the therapeutic potential of the Zhuang-Gu-Fang for postmenopausal osteoporosis (PMOP) and further revealed that its therapeutic effect was related to the balance of bone metabolism and the recovery effects of bone-related factors Leptin, Ghrelin, and PYY." (PMID 33281915, 2020).
pulmonary TB (1 paper, 2013). "In this first published study examining PYY in pulmonary TB, the key finding was that a high pre-treatment PYY was an indicator of poor prognosis for gains in both appetite and BF during treatment." (PMID 23358528, 2013).
rectal NETs (1 paper, 2020). "Others (e.g., Glucagon-like Peptide (GLP) and peptide YY (PYY)) are used in immunophenotypic classification and prognosis of rectal NETs." (PMID 32429087, 2020).
rectal tumors (1 paper, 2023). "PYY and PP have been observed in rectal tumors, and the density of cells expressing PYY in these tumors was small-moderate compared to those cells containing PP." (PMID 37373115, 2023).
renal dysfunction (1 paper, 2023). "The concentrations of adipsin, ghrelin, GIP, and PYY were 1.2 times greater in the group of individuals with renal dysfunction." (PMID 37623488, 2023).
renal failure (1 paper, 2006). "Renal failure is known to be associated with high levels of PYY, and it is currently unclear whether this represents the active PYY3–36." (PMID 16420657, 2006). "A significant difference in PYY levels between patients and the control group is still clearly apparent, even with the removal of data for the four renal failure patients." (PMID 16420657, 2006). "It is of interest that in all four patients who had renal failure we found high levels of ghrelin and PYY." (PMID 16420657, 2006). "Of 16 patients, four had renal failure and significantly higher PYY levels than those patients that did not have renal failure (day 3 in ICU, 62.2 ± 5.2 versus 34.0 ± 5.9 pmol/l, p < 0.05)." (PMID 16420657, 2006).
Sepsis (1 paper, 2007). Sepsis is defined as life-threatening organ dysfunction caused by a dysregulated host response to infection. "Baseline plasma concentrations of both CCK and PYY were not related to gender (P = 0.82), the APACHE II score on the study day (P = 0.40), serum creatinine (P = 0.28), the type of sedation, the use of inotropes or acid suppression, the presence of sepsis, or prior enteral nutrition." (PMID 18154642, 2007).
short bowel syndrome (1 paper, 2021). "The role of PYY has already been discussed in the pathogenesis of patients with short bowel syndrome, but has so far been less well-known in HOS." (PMID 34095201, 2021).
systemic sclerosis (1 paper, 2013). A chronic disorder, possibly autoimmune, marked by excessive production of collagen which results in hardening and thickening of body tissues. "Thisincrease in circulating PYY in patients with systemic sclerosis seems to be secondary to thediarrhea, rather than a primary cause, and is probably an attempt to slow downgastrointestinal motility." (PMID 23292145, 2013).
tobacco use disorder (1 paper, 2020). "Peptides that regulate appetite such as glucagon-like peptide 1 (GLP-1), ghrelin, leptin, peptide YY, and neuromedin U are expressed throughout the brain reward circuitry, providing strong evidence that food addiction and tobacco use disorder share overlapping gut–brain axis mechanisms." (PMID 33334010, 2020).
tuberculosis (1 paper, 2020). A chronic, recurrent infection caused by the bacterium Mycobacterium tuberculosis. "A more general role for PYY in weight regain is consistent with the fact that high levels of PYY predict lower weight and appetite regain in patients that recover from weight loss associated with tuberculosis." (PMID 32342267, 2020).
ulcerative colitis (1 paper, 2025). An inflammatory bowel disease involving the mucosal surface of the large intestine and rectum. "Utilizing IL10-deficient mice, a classic model for ulcerative colitis, we found a substantial reduction in the number of PYY-positive cells in colonic tissues compared to control mice." (PMID 40340969, 2025).
metabolic disorders (20 papers, 2012 to 2026). "At 3 years postpartum, longer lactation duration was associated with higher levels of ghrelin and peptide YY, both involved in appetite regulation and associated with reduced risk of metabolic disease." (PMID 29186142, 2017). "Importantly, altered PYY levels are associated with several metabolic disorders which also alter bone mass, indicating a possible role for PYY in bone homeostasis." (PMID 22792209, 2012). "Among its multiple positive influences on metabolic disease, IL-22 injection in obese mice leads to increased serum PYY levels which is thought to contribute to the reduction in food intake and weight." (PMID 30639417, 2019). "Finally, it will explore the new treatment possibilities of PYY for IR and metabolic diseases based on current research progress." (PMID 41788781, 2026). "Because modified levels of PYY are correlated with various metabolic disorders that also impact bone mass, PYY may potentially exert an influence on bone homeostasis." (PMID 38725663, 2024). "Gut-pancreatic peptides such as glucose-dependent insulinotropic polypeptide (GIP), glucagon, amylin, and peptide YY (PYY) are of particular interest due to their distinct pharmacological benefits and therapeutic promise in metabolic disorders." (PMID 42307179, 2026). "The investigated parameters related to metabolic disorders included sirtuin 1 (SIRT-1), sirtuin 3 (SIRT-3), sirtuin 6 (SIRT-6), irisin (IRS), myostatin (MSTN), peptide YY (PYY), glucagon-like peptide 1 (GLP-1), and dipeptidyl peptidase 4 (DPP-4)." (PMID 39124846, 2024). "Additionally, restoration of butyrate levels has been shown to improve blood glucose regulation through modulation of glucagon-like peptide-1 (GLP-1) and peptide YY (PYY) secretion, supporting broader benefits in metabolic disease." (PMID 40806090, 2025).
cancer (15 papers, 2014 to 2025). A tumor composed of atypical neoplastic, often pleomorphic cells that invade other tissues. "Some of these genes, such as TRIP13, PYY, are known to be cancer-associated." (PMID 29378509, 2018). "The first important aim that must be achieved is to perform a systematic study on the expression/role of NPY, PYY, PP, and their receptors in different types of cancers." (PMID 37373115, 2023). "In this section, the participation of NPY, PYY, and PP in the development of many cancer types is reviewed." (PMID 37373115, 2023). "Most studies regarding the involvement of the NPY peptide family in tumor development have focused on NPY, whereas only incomplete or scarce data are currently available about the involvement of PYY/PP in many cancer types." (PMID 37373115, 2023). "Using NPY/PYY/YRs expression/plasma levels as cancer biomarkers/prognostic factors requires more in-depth studies to confirm the findings reported in this section." (PMID 37373115, 2023). "These are noteworthy that CXCL12 and EPB41L3 were verified by the GEPIA in COAD and READ cancer types while SCNN1B and PYY were documented only in COAD cancer type by the GEPIA." (PMID 35333898, 2022). "Indirect mechanisms that lead to a risk reduction for cancer development include increased postprandial secretion of satiety hormones such as GLP-1, peptide YY (PYY), and oxyntomodulin (OXM)." (PMID 35910464, 2022). "Investigation of PYY and NPY, have collectively revealed that they are implicated in a variety of inflammatory disorders, such as autoimmune diseases, asthma, atherosclerosis, and cancer." (PMID 34572888, 2021). "Beyond its anti-inflammatory effects, PYY may exhibit anti-cancer properties." (PMID 40340969, 2025). "Currently available data on the involvement of neuropeptide Y (NPY), peptide YY (PYY), and pancreatic polypeptide (PP) and their receptors (YRs) in cancer are updated." (PMID 37373115, 2023). "Current data show the peptidergic system’s high potential for cancer diagnosis, treatment, and support using Y2R/Y5R antagonists and NPY or PYY agonists as promising antitumor therapeutic strategies." (PMID 37373115, 2023). "M-SJDBT significantly inhibited cancer-induced induction of both GLP-1 and PYY by approximately 63.2% and 44.9%, respectively." (PMID 24963216, 2014). "Some researchers also suggest that microbial-related metabolites, such as propionate, butyrate, PYY, and Bcl3, could be useful for PDAC diagnosis and classification, although the cancer-specific nature of these changes has yet to be fully elucidated." (PMID 40102723, 2025). "Moreover, the involvement of pancreatic polypeptide (PP) and peptide YY (PYY), members of the NPY peptide family and less studied in cancer, will also be reviewed." (PMID 37373115, 2023). "Although the involvement of peptides in cancer is a promising line of research to develop specific antitumor therapeutic strategies, there is much to investigate regarding the participation of NPY, PYY, and PP in cancer progression: basic information on many tumors is scarce, incomplete, or absent." (PMID 37373115, 2023). "Hence, it is crucial to know the YR types that express tumor cells, the G proteins involved in these mechanisms, and the signaling pathways activated by the different YRs in order to explain cancer/anticancer actions mediated by NPY and PYY and to develop specific antitumor strategies." (PMID 37373115, 2023).
tumor (13 papers, 2014 to 2025). "Instead of isolated proteins, we identified a downregulated network of EEC markers (CHGA, GCG, PYY, NEUROD1) associated with tumor processes, reduced survival, and poor chemotherapy responses." (PMID 41303610, 2025). "PYY was observed in the perinuclear region of stromal cells placed in small clusters and scattered and distributed by the tumor parenchyma." (PMID 37373115, 2023). "One tumor expressed PYY diffusely, and 9 others had focal staining." (PMID 40553402, 2025). "Canonical EEC markers and hormone genes (e.g., GCG and PYY) were likewise reduced in tumor tissue." (PMID 41303610, 2025). "The improved structural stability of PD NFs and PYY NFs ensures their selective tumor accumulation, effective intra-cellularization, and high photothermal conversion in the biological environment, leading to tumor ablation without recurrence or detectable side effects." (PMID 39464634, 2024). "High serum/tumor tissue PYY levels were reported in these animals; however, it is currently unknown whether PYY is involved in tumor formation or development." (PMID 37373115, 2023). "Recent studies have shown that PYY exists in a variety of tumor tissues, and the decrease in its expression may be related to the occurrence and progression of tumors, and it has an inhibitory function on a variety of tumors." (PMID 32462020, 2020). "Since GCG encodes the precursor of GLP-1, the observed reduction in GCG and other key EEC markers (CHGA, NEUROD1, PYY) in tumor tissue, combined with these external clinical data, suggests that EECs and incretin hormones may exert an anti-tumor role in colorectal carcinogenesis." (PMID 41303610, 2025). "However, the detailed mechanism by which PYY inhibits tumor cells is unclear." (PMID 32462020, 2020). "Nonetheless, an analysis of metastatic versus non-metastatic COAD tissue revealed that EEC-related genes (GCG, PYY, CHGA, NEUROD1) were consistently downregulated in both tumor and normal tissue and between metastatic and normal tissue." (PMID 41303610, 2025). "As expected, the tumor cells tended to show lower expression of differentiation genes such as enterocyte markers (CA1, CA2, and CLCA1) and endocrine cell markers (PYY and GCG)." (PMID 35974387, 2022). "Like sorting nexin-18, PYY was never detected in the deep region of the tumor and was identified as a less-abundant protein in superficial tumor tissue." (PMID 39195201, 2024). "Data regarding the proliferative/antiproliferative actions mediated by PP on tumor cells are currently lacking; however, PYY and its fragments exert, in general, an antitumor effect by blocking tumor cell growth, migration, and invasion." (PMID 37373115, 2023). "IHC analysis, such as Syn, CgA, CD56, PYY, and thyroglobulin, could also promote the diagnosis of POC, while in our cases, both tumor tissues were positive for Syn, CgA, and CD56." (PMID 33019380, 2020). "For example, PYY, CD177, PEG3, and FAM83D, were observed in more than 11 normal samples, while less than 3 were observed in tumor samples." (PMID 30538721, 2018).